CD4 (CD4 molecule)
Diseases named in the same sentence as CD4 in open-access papers (continued):
Sharing a sentence is not in itself a finding about the gene and the disease.
tumor (continued). "We assume that the densities of immature dendritic cells and naive CD4+ and CD8+ T cells remain constant throughout the tumor tissue." (PMID 35015785, 2022). "The number of peripheral blood CD4+T lymphocyte and CD8+T lymphocyte continued to increase as the tumor shrank." (PMID 36273133, 2022). "In the role of anti-tumor immunity, mast cells secreted CCL3 and CXCL10 to recruit NK cells, CD4+ helper T cells, and CD8+ cytotoxic T cells." (PMID 35563678, 2022). "Naive and memory T cells, both CD4+ and CD8+, showed equal capacity to induce tumor cell kill in vitro, although it should be noted that memory T cells were evaluated without further distinction between effector and central memory subsets." (PMID 36271507, 2022). "The roles of lymphoid cells such as CD4+ TILs and CD8+ TILs have been well elucidated in anti-tumor responses, while the complex role of myeloid cells such as CD14+ monocytes and CD15+ granulocytes have been relatively underexplored." (PMID 36203421, 2022). "Chemokines are conceived to recruit core immune cells (CICs) of the immune system (including B, CD4+T, CD8+T, macrophage, neutrophil, and dendritic cells) to the on-site of infection or sterile injury (including tumor progression)." (PMID 35774781, 2022). "The population, proliferation and cytotoxic activity of CD8+ T cells were significantly increased in the tumor of the mice co-treated with MAC and anti-PD-L1 antibody, whereas the population and proliferation of CD4+ T cells were unchanged." (PMID 35265193, 2022). "Then, we found less abundant CD4 TCM and CD8+ Temra cells and more NKT and CD8+ TEM cells in LC tumour tissue compared to GM samples." (PMID 36336787, 2022). "We found that neoantigen vaccinated tumor-bearing mice display more CD11ahiCD49dhi CD4 T cells and lower percentage of Tregs in the TME compared to vehicle-treated tumor-bearing mice." (PMID 36569934, 2022). "Data from the canine patients showed that compared to tumor only SBRT, ENI treatment reduced CD4 and CD8 T lymphocyte counts in nasal lavages which have been shown to be representative of the TME25." (PMID 36385142, 2022). "We identified a high degree of inter-tumor heterogeneity in DLBCL samples and prominent immunosuppressive features in CD4+ regulatory T cells (CD4+ TREG) and exhausted cytotoxic CD8+ T cells (CD8+ TEXH)." (PMID 35601491, 2022). "Since we only implanted OVA-LY2 cells in the flank tumor, if treating mice with ENI was reducing epitope spreading, we would expect a reduction in OVA-specific CD4 T cells circulating in the blood." (PMID 36385142, 2022). "Subsequent flow cytometry (FACS) and immunohistochemistry (IHC) analysis revealed that administration of AN3025 led to decreased Tregs population, increased CD4+ and CD8+ T cell numbers in the tumor." (PMID 35251028, 2022). "We observed AE1/AE3 staining in all three SNmet samples and identified scattered CD4 and CD8 staining within the tumor area." (PMID 34165864, 2022). "TGFβ produced by Bregs can increase the ability of TGFβR1 and TGFβR2 expressing MDSCs to produce cytotoxic reactive oxygen species and nitric oxide (NO), resulting in efficient inhibition of CD4+ and CD8+T cell anti-tumour responses." (PMID 35350071, 2022). "We found that both CD4+ and CD8+ T cells were capable of mediating tumor cell killing following BsAb-mediated activation." (PMID 35990699, 2022). "Type 1 T-cells, such as CD4 T-helper 1 (Th1), facilitate antigen presentation, whereas CD8 cytotoxic T-cells (CTL) accelerate tumor destruction." (PMID 36145510, 2022). "Consistent with this, B cells have been shown to sustain inflammation and CD4+ and CD8+ T-cell numbers in the tumor microenvironment." (PMID 35684019, 2022). "Specifically, we analyzed CD4+/Foxp3+ T regulatory cells (T-regs), CD4+/Foxp3− helper T cells (Th-cells), CD8+ cytotoxic T cells (Tc-cells), CD20+ B-cells, CD68+ macrophages, and CK+ tumor cells." (PMID 35565427, 2022).
tumor (continued). "The current study is aimed at testing CD4, CD8, CD68, and MMP9 immunohistochemistry of DLBCL activities with the prognosis of the tumor." (PMID 35083113, 2022). "For instance, intratumorally administration of DNX2401 increases the infiltration of CD4+ and CD8+T cells in the tumor while significantly reducing the number of Tregs." (PMID 36159398, 2022). "A comparing analysis in both TCGA‐LUAD and TCGA‐SKCM datasets showed that the PAPPA2‐Mut group had revealed higher activated CD4 memory T cells and lower Treg cells than PAPPA2‐WT tumours." (PMID 35811392, 2022). "Inflamed TMEs, also known as “hot” tumors, are characterized by an abundance of cytokine-secreting CD4+ and cytotoxic CD8+ T cells, myeloid cells, and monocytes in the tumor core." (PMID 36297203, 2022). "In this study, we show that among CD4+ TILs, the cells that coexpressed PD-1 and ICOS were enriched for tumor-reactive T cells in patients with HNSCC or CRC." (PMID 35439168, 2022). "Our results demonstrated that targeting EZH2 therapy reprograms the tumor immunogenicity by inducing a significant increase in CD4+ and CD8+ T cells within the tumor microenvironment." (PMID 35912007, 2022). "Stimulating CD4+ and CD8+ T-cell responses toward TAA motivates a strong immune response, though specific against targets functionally relevant to tumor cells." (PMID 36510217, 2022). "Staining of CD8+ T cells, conventional CD4+FOXP3- T cells (Tconv cells), CD4+FOXP3+ regulatory T cells (Treg cells), CD20+ B cells, and CD68+ macrophages was performed, and cell density was evaluated in both the tumor and its stroma." (PMID 36201479, 2022). "The densities of specific immune cells (CD3+, CD4+, CD8+) within the tumor microenvironment were examined by immunohistochemical." (PMID 35719959, 2022). "The percentages of tumor‐infiltrating immune cells including CD8+ T cells and CD4+ T cells were increased upon OncoAd treatment." (PMID 35762456, 2022). "CD4+ T cells attack tumor cells in multiple ways, and CD8+ T cells release a variety of cytokines to clear tumor cells upon recognition of tumor-specific antigens via T-cell receptors." (PMID 36230568, 2022). "Fresh tumor tissue samples from 33 NSCLC patients were collected and similarly analyzed to confirm the immune state of patients with VISTA expression on CD4+ T cells by flow cytometry." (PMID 35122478, 2022). "T-VEC is a genetically modified live HSV-1 which decreases the infiltration of CD4+FoxP3+ Tregs and CD8+FoxP3+ suppressor T cells into the tumor microenvironment." (PMID 35865534, 2022). "As the tumor size increases, the presence of CD4+ CCR6+ CCR5+ CXCR3− and CD4+ CCR6+ CCR5− CXCR3− T cells also increase, which means that Th17/Th1 and Th17 cells’ presence is directly correlated with the size of the tumor in CRC liver metastasis." (PMID 36551555, 2022). "Triggered by hyperthermia treatment at tumor sites, the PTX@TF was rapidly released and entered cancer cells, creating synergies with marimastat, thus leading to improved tumor infiltration of CD8+ (4.2-fold) and CD4+ T cells (1.7-fold)." (PMID 36015215, 2022). "Released DAMPs from tumor cells can bind to the pattern-recognition receptors on the APCs, thereby stimulating the APCs to present endocytosed antigens to CD8+ and CD4+ T cells through major histocompatibility complexes (MHCs)." (PMID 35740542, 2022). "After treating with PEG-rGO-FA-IDOi nanosheets, CD45+ leukocytes, CD3+ CD4+ T cells and CD3+ CD8+ T cells in the distant tumor would increase." (PMID 35497343, 2022). "This renders CD39 a candidate marker for activated, more differentiated, and antigen-specific CD4+ T-cells in SARS-CoV-2 infection, similar to the already known CD39 expression by tumor-reactive T-cells." (PMID 35746736, 2022). "A total of six types of tumor immune cells including B cell, CD8+ T cell, CD4+ T cell, macrophage, neutrophil, and dendritic cell were analyzed for the correlation with GXYLT2 expression in BLCA." (PMID 36263004, 2022).
tumor (continued). "Treg cells, as the main immunosuppressive cells in mouse and human tumors, are T cell subsets with phenotypic characteristics of CD4+CD25+Foxp3+, which play an important role in regulating the tumor microenvironment and promoting tumor immune avoidance." (PMID 35445056, 2022). "Fortunately, NRC3 was remarkably infiltrated by activated T cell populations such as CD4+ and CD8+ T, which should have been related to anti-tumor immunity." (PMID 35590418, 2022). "In anti-PD-1 monotherapy, several clinical and preclinical studies have concluded that infiltrating and circulating CD4+ and CD8+ T cells are important in the anti-tumor effect of ICIs, with major anti-tumor responses biased to the CD8+ T-cell effects." (PMID 35433707, 2022). "While ONP-302 treatment slowed B16.F10 tumor growth as compared to control treated mice, ONP-302 treatment resulted in increased percentages of PD-1+ CD4+ T cells, PD-1+ CD8+ T cells, PD-1+ NK cells, and PD-L1+ myeloid cells." (PMID 36059473, 2022). "CD4 and CD8 staining methods were used to evaluate the effect of GM on T-cell infiltration in tumor tissues in vivo." (PMID 35875081, 2022). "It rebalances the TME towards an antitumor immune response by reducing the immunosuppressive myeloid derived cells and increasing the tumor fighting CD3+ T cells and, in particular, CD4+ T cells which in other studies is an indicator of an effective therapy." (PMID 35681695, 2022). "Analysis of the immune landscape in the tumor microenvironment showed an increase of CD4+ Th1 cells and CD8+ cytotoxic T cells but a decrease of CD4+ Treg cell infiltration." (PMID 35572581, 2022). "Of note, compared with IL1R1− Treg cells or CD4+ T cells, IL1R1+ Treg cells expressed higher levels of CXCR6, which was recently reported to be critical for anti-tumour activity of cytotoxic T cells in a mouse model." (PMID 35545675, 2022). "For T cells, we focused on T cell exhaustion, which was revealed in both CD4+ and CD8+ T cells from tumor tissues." (PMID 36104333, 2022). "We performed immunohistological staining for CD8-, CD4-, and CD68-positive tumor-infiltrating immune cells and measured relative levels of cytokines produced in Sftpc-WT and Sftpc-KO mice." (PMID 35326737, 2022). "Locally accumulated CD4+ and CD8+ T cells do not only represent an important source for the release of pro- and anti-inflammatory cytokines into the tumor microenvironment, but are also key targets of intratumoral cytokine signaling." (PMID 36428508, 2022). "We propose that baseline peripheral blood CD4+CD45RA− T-cell counts can be used as a biomarker for predicting the efficacy of ICIs, especially for the second line and beyond patients, whose tumor tissue acquisition is difficult." (PMID 35844502, 2022). "GM-CSF also increased immunoglobulin production, DC, CD4+, and CD8+ T cell counts, and tumor-specific lymphocyte cytotoxicity when administered together with the MB49 bladder cancer stem cell vaccine in a mouse model." (PMID 35865534, 2022). "Cells that recognize MHC I will become CD8+ T cells with cytotoxic effects on tumor cells and virus-infected cells, while cells that recognize MHC II become CD4+ T cells." (PMID 36497422, 2022). "At the same time, the expression of CD4+ T cells, CD8+ T cells, M2 macrophages, mast cells, neutrophils, NK cells, T helper cells, Tregs and dendritic cells in the high-risk subgroup was significantly upregulated, indicating that the high-risk subgroup could be identified as an immune hot tumor." (PMID 36606199, 2022). "Compared to irradiation alone, the combination treatment of curcumin and radiation promoted the infiltration of CD4+ T cells, CD8+ T cells, and CD11c+ dendritic cells in the spleen and tumor tissues of mice and effectively enhanced the antitumor immunity." (PMID 36238646, 2022).
tumor (continued). "In our study, the comparison between the methylation patterns of hTERT promoter in CTCL tumor cells and healthy cells revealed that THOR is unmethylated in healthy CD4+ cells and in stem/progenitor cells." (PMID 33715271, 2022). "A majority of studies that aim to classify the subset of TILs in the tumor microenvironment use IHC markers for surface proteins, such as CD20 and CD79a for B cells, CD3 for T cells, CD4 and CD8 for T cells, and FOXP3 for regulatory T cells." (PMID 36686160, 2022). "Results illustrated that the infiltration of CD4+, CD8+ T cells and NK cells was promoted after PSB-mediated hydrogen treatment in tumor tissue." (PMID 35705974, 2022). "CD4+ helper T cells and cytotoxic CD8+ T cells play an important role in tumor prevention by targeting antigenic tumor cells, and CD8+ T cells are associated with better clinical outcomes and immunotherapeutic responses in many cancers." (PMID 35860566, 2022). "Peripheral T lymphocytes CD4+ and CD8+ play a key part in anti-tumor immunity, and CD4+ T cells help in recruiting CD8+ T cells, while CD8+ T cells directly attack and kill tumor cells." (PMID 36500466, 2022). "As we observed improved tumor infiltration of T cells with α-OX40, we evaluated the proportion of proliferating CD8+ and CD4+ T cells using expression of the proliferation marker Ki-67." (PMID 35681672, 2022). "Analysis of the T cell subtypes revealed that CD4+ T cell infiltration was highly variable and that CD8+ T cells comprised approximately 5% of CD3+ lymphocytes in the primary tumor, ascites, and metastases." (PMID 36077756, 2022). "A single irradiation with 2 Gy increased the ability of tumor-specific CD4+ and CD8+ T cells to migrate into the tumor." (PMID 36532071, 2022). "Next, the epitope-bound APCs activate tumor-specific CD4+ Th cells and CD8+ CTL that migrate to the tumor site and assist in killing." (PMID 35053449, 2022). "In a favorable immune context, tumor antigens are processed and presented by antigen presenting cells (APCs), triggering the activation of CD4+ and CD8+ T cells, ultimately eliminating the tumor." (PMID 36015189, 2022). "The trigger of an anti-tumor immune response starts with major histocompatibility complex class I (MHC-I) and II (MHC-II) presenting tumor antigens to CD8+ and CD4+ T cells, respectively." (PMID 36365247, 2022). "Patients in whom glioblastomas were surgically resected received another personalized peptide neoantigen vaccine that elicited neoantigen-specific CD4+ and CD8+ T-cell responses and showed an accumulation of neoantigen-specific T cells in the tumor site." (PMID 36477638, 2022). "This supports the important roles of CD4+ and CD8+ T-cells in the tumor microenvironment of HNSCC, as indicated in recent literature." (PMID 36157879, 2022). "Compared to the tumor-bearing control, ATRA treatment alone significantly decreased the differentiation of Th2 cells and Tregs, but the expression level of perforin in CD4+ T cells was obviously decreased; furthermore, the Th1 subset showed a decreasing trend." (PMID 36389684, 2022). "Similar changes were also observed in analyzing granzyme B and Ki-67 expression by tumor infiltrating and splenic CD8+ and CD4+ T cells except Ki-67 expression in splenic CD4+ T cells." (PMID 35514996, 2022). "Tumor-infiltrating immune cells are represented by six types, namely B cells, CD8+ T cells, CD4+ T cells, macrophages, neutrophils and dendritic cells." (PMID 35278064, 2022). "We found that the IFNγ levels of total, CD4+ and CD8+ T cells in visceral fat increased on day 5, suggesting 5Aza's potential role in enhancing the anti-tumor activity of T cells." (PMID 34976218, 2022). "T cells express IL-2 and IFN-γ receptors stimulated by the corresponding cytokines produced by CD4+ Th1 cells to activate CD8+ cytotoxic T cells and have a killing effect on tumor cells." (PMID 36012134, 2022).
tumor (continued). "They found that, in comparison with the immune cell population of tumor-free lungs (TFL), MPM TILs had a much higher number of Tregs (2.2% vs. 12.8% of CD4+ population, respectively), and that these highly expressed TIGIT (72.5% of cells)." (PMID 35327475, 2022). "In contrast to αβ T cells (CD4+, CD8+ T cells), γδ T cells recognize and kill transformed cells by endogenous tumor-derived pyrophosphates." (PMID 35740542, 2022). "Anti-PD-L1 monotherapy increased intra-tumor immune cell infiltration of all cell subsets analyzed, with statistically significant changes in CD3+ T cell, CD4+ T cell, and natural killer (NK) cells." (PMID 35849586, 2022). "NK cells prime DCs, increasing tumor antigen presentation to cytotoxic CD8+ T cells and the polarization of CD4+ T cells toward an antitumor Th1 phenotype." (PMID 35912227, 2022). "LAG-3 is expressed by many T cell subsets, including: CD4 T helper cells, cytotoxic CD8 T cells, activated T cells, NK T cells, effector CD4 T cells, regulatory T cells, CD8 tumor-infiltrating lymphocytes and tumor-infiltrating antigen-specific CD8 T cells." (PMID 35954196, 2022). "The frequencies of CD4+IL-4+, CD4+IL-17+ and CD8+IL-10+ showed significant increases in laryngeal SCC patients with tumor size ≤ 3 cm (P = 0.024, P = 0.048, P = 0.001, respectively)." (PMID 36376825, 2022). "We investigated the infiltration of CD4+ and CD8+ T cells in tumor tissues to characterize the effect of the combination of fascaplysin and anti−PD−1 on the immune response against tumors in vivo." (PMID 36430250, 2022). "Tumor-infiltrating CD3+CD8+ and CD3+CD4+ T cells were greatly increased in mice treated with PMA-TCLV and aPD-L1 compared with in the groups treated with TCLV or control group." (PMID 35217574, 2022). "Stimulated CD4+ T helper 1 cells secrete the effector cytokines interferon-gamma (IFN-γ) and tumor necrosis factor alpha (TNF), which induce senescence in tumor cells." (PMID 35563820, 2022). "We have also revealed a role for CD4+ and CD8+ T cells and ADCC in combination treatment induced tumor regression in a HER2pos BC model." (PMID 35710296, 2022). "Adoptive immunological memory mediated by tumor reactive CD4+ and CD8+ T cells play a key role in protective immunity to tumor antigens." (PMID 35710296, 2022). "In addition, the inhibition of autophagy drastically reduced the proliferation of MHC-II-restricted CD4+ T cells, suggesting that the delivery of tumor antigens to the autophagy pathway could become a novel strategy to enhance the antitumoral CD4+ T cell response." (PMID 36139357, 2022). "Overall, the results showed that as treatment continued, the effector memory subset of CD4+ T cells was increased by adding SKI-G-801 in both the TC1 and C3PQ tumor models compared to treatment-naive tumors (*p<0.05, ***p<0.001)." (PMID 35356198, 2022). "In the tumor-draining lymph nodes, APCs’ antigen-loaded MHC (pMHC) I and II engage interactions with the TCR of CD8+ or CD4+ T cells, respectively." (PMID 35269922, 2022). "Immunohistochemistry analysis revealed that the tumour microenvironment of mPDAC was infiltrated by CD8 T-cells, among which 2.9% of cells were CD8+ and 21.7% were CD4+." (PMID 36077801, 2022). "Both the density and proportion of CD4+ Granzyme B+ and CD8+ Granzyme B+ T cells exhibited an increase post-vaccination, indicating the enhancement of the infiltration of T cells into tumor tissues." (PMID 36248865, 2022). "T CD4+ and CD8+ lymphocytes tolerance is also increased by β-catenin in DC cells in the tumor microenvironment." (PMID 37305016, 2022). "Recently, tumor-infiltrating lymphocytes (TIL), especially CD4+ T cells, cytotoxic CD8+ T cells, and γδ-T cells have been associated with clinical benefit and favorable prognosis in the tumor microenvironment." (PMID 35563678, 2022).